NOS3 (nitric oxide synthase 3)
Diseases named in the same sentence as NOS3 in open-access papers (continued):
Sharing a sentence is not in itself a finding about the gene and the disease.
diabetes (continued). "In this research, the increase in NOS-3 and even more so in Akt and PI3K p85α protein expression in response to estrogen replacement inferred the regulation mechanism of estrogen on NOS-3 in this diabetes model." (PMID 23209733, 2012). "According to the literature, early nephropathy occurring in diabetes is associated with increased intrarenal NO production, mainly mediated by neuronal nitric oxide synthase (NOS1, nNOS) and endothelial nitric oxide synthase (NOS3, eNOS)." (PMID 39061907, 2024). "Although the role of the NOS3 polymorphisms in the risk of developing diabetes complications has not been demonstrated, lower NOS3 concentrations were observed in patients with diabetic nephropathy or after kidney transplantation." (PMID 39061907, 2024). "In 490 T2DM patients and 485 healthy controls, NOS3-rs3918188 was associated to susceptibility to T2DM; the rs1800783 polymorphism (R2 = 0.1404 with rs3918226) predicted DKD, and family history of diabetes was closely associated with rs11771443 (R2 < 0.1 with rs3918226) polymorphism in DKD." (PMID 38858654, 2024). "Another significantly enriched pathway involving ASD target genes was the AGE-RAGE signaling pathway which may be closely related to the influence of diabetes regulatory gene NOS3." (PMID 34765091, 2021). "Furthermore, diabetic NOS3−/− mice displayed an increased percent of fibrosis (using ImageJ) in Masson's trichrome ‐stained sections 24 weeks after diabetes, which was reduced by treatment with homoarginine." (PMID 33713581, 2021). "Notably, the protein most predictive of diabetes status in the random forest model was NOS3 (also known as endothelial NOS) which is known to play a key role in CVD-protection via the generation of the vasodilator nitric oxide in blood vessels." (PMID 33279861, 2021). "As AGRT1, IL6, NOS3 and TNFA genes are common candidates for diabetes and associated complications, drugs that target these might mitigate multiple risk factors simultaneously." (PMID 33820928, 2021). "In stratified analyses, homozygosity for the NOS3 T allele in obese white participants but not in those whose BMI <30 kg/m2 was associated with an elevated risk of diabetes (OR = 1.47, p = 0.02) when compared to the common GG genotype." (PMID 24278136, 2013). "Similarly, NOS3 connects Alzheimer’s disease and Diabetes mellitus with HCM and DCM." (PMID 36385157, 2022). "Furthermore, diabetic NOS3−/− mice had a significant reduction in ejection fraction (EF) and fractional shrinking (FS) compared with non‐diabetic controls at 22 weeks of diabetes, an effect significantly restored using homoarginine treatment." (PMID 33713581, 2021). "Therefore, to help address this sex issue, and to facilitate the experimental use of both sexes of Nos3‐/‐ mice, we sought to establish whether inducing equivalent diabetes results in a comparable onset of DKD in male and female Nos3‐/‐ mice." (PMID 31535473, 2019). "Although a similar effect of diabetes on CAT1 in saphenous artery endothelium has not been reported thus far, downregulation of arginine transporter(s) may contribute to the observed dependence on arginine resynthesis in diabetes to maintain adequate intracellular arginine availability for NOS3." (PMID 25033204, 2014). "A progressive decrease of endothelial nitric oxide synthase (NOS-3) expression, due to long term exposure of high glucose, advanced glycation end-products (AGEs) accumulation, or a combination of both processes, was discovered to be very important in the context of diabetes." (PMID 23209733, 2012). "Next we determined if diabetes and/or homoarginine altered the expression of other NOS isoforms in kidneys from NOS3 −/− mice." (PMID 33713581, 2021). "In total there were 44 out of 973 (4.5%) proteins that contributed significantly to the prediction of diabetes (FDR-corrected p<0.05) in the random forest model, the most important being NOS3, HGF, PON3, IGSF3, and ADGRG1." (PMID 33279861, 2021).
diabetes (continued). "This study shows that equivalent diabetes induces a comparable onset of DKD in male and female Nos3‐/‐ mice, demonstrating that it is possible to include males and females together in studies of DKD." (PMID 31535473, 2019). "We analyzed the distribution of NOS3 and DDAH2 genetic variants across three groups: Group I (STEMI without diabetes, n=71), Group II (STEMI with diabetes, n=77), and Group III (healthy controls, n=75)." (PMID 40144407, 2025). "Finally, some links between DN and DR/DNp were found with NOS3, and VEGFA, mainly due to the number of factors and genes interactions that complement each other leading to diabetes disease progression." (PMID 35069435, 2021). "Our results show that neither diabetes nor homoarginine affected NOS1 or NOS2 gene expression in NOS3−/− mice." (PMID 33713581, 2021). "The gene expression level of NOS3 was lower in diabetic WT mice than in non-diabetic WT animals, whereas it was not affected by diabetes in AT2R−/y mice." (PMID 28361992, 2017). "Between the two nitric oxide synthases tested in the present study, Nos1 (neuronal) expression was significantly decreased (p-value < 0.001) in diabetes, while Nos3 (endothelial) expression was not significant (p-value = 0.06)." (PMID 20979611, 2010). "Conversely, in type 2 diabetes mellitus model, a hyper-insulin environment, both in vivo and in vitro experiments indicate that KLF5 attenuates VEGF-induced endothelial migration and proliferation and compromises angiogenic function by inhibiting the expression of NOS3." (PMID 33493334, 2021). "In the current study, we tested the hypothesis that the protective effect of homoarginine in renal and cardiac functions in diabetes is independent of NOS3." (PMID 33713581, 2021). "However, this association did not remain statistically significant after adjusting for diabetes duration, HbA1c, diastolic BP and the presence of other DKD-associated polymorphisms located in three different genes, namely AGER-429T/C and 2184A/G, LTA 252A/G, and NOS3 774C/T and E298D." (PMID 26594247, 2015).
Obesity (60 papers, 2009 to 2026). Accumulation of substantial excess body fat. "The results showed a positive correlation between rs1799983 NOS3 distribution and alcohol and obesity risk factors (p = 0.009 and 0.02, respectively)." (PMID 33809023, 2021). "The NOS2 rs2297518 [A/G] and NOS3 rs1799983 [G/T] genetic variations were associated with insulin resistance, obesity, and/or a higher BMI in several populations." (PMID 33924357, 2021). "We find UHRF1BP1 and ILRUN mediate the effect of obesity on CAD whereas methylation sites within NOS3 and CKM mediate the effect of their associated-risk factors on CAD." (PMID 33574266, 2021). "Increased gene expression of NOS3 may cause decreased lipolysis of subcutaneous adipose tissue in obesity." (PMID 36532520, 2022). "The SNP (rs1799983) in the NOS3 gene has been associated with obesity." (PMID 36532520, 2022). "One is the result of synergism between AGT TT, PAI-1 4G/4G, and other unidentified genetic factors associated with FH and/or aging; the other pathway results from synergism between the NOS3 GA+AA genotype and other unidentified genetic factors associated with FH and/or obesity." (PMID 19838007, 2009). "Hence, regarding the NOS3 gene, only a small proportion of the Latin American population may be predisposed to obesity." (PMID 36532520, 2022). "Future clinical studies should focus on the expression and function of NOS3 in adipose tissues of patients with obesity and/or related diseases." (PMID 37897505, 2023). "Lastly, the NOS3 enzyme has been identified to play an essential role in lipolysis modulation, and obesity condition per se has profound effects on covalent modification of the NOS enzyme by insulin-dependent activation of protein kinase B." (PMID 33924357, 2021). "Other SNPs associating with sarcopenia include, fat mass and obesity associated gene (FTO) rs9939609 from fat, sex hormone Estrogen receptor 1 gene (ESR1) rs4870044, nitric oxide synthase 3 gene (NOS3) rs1799983 in the vascular endothelium, and Thyrotropin-releasing hormone receptor (TRHR) rs783255." (PMID 40772803, 2025). "Therefore, we generated a tamoxifen-induced adipocyte-specific NOS3 knockout mouse model (A-NOS3 KO) to investigate the function of adipocyte NOS3 in diet-induced obesity directly." (PMID 37897505, 2023). "When this was done, the OR for the interaction term for obesity and the NOS3 G894T TT genotype in whites was 1.71 (95% confidence interval (CI) = 1.02–2.87) and the p-value for interaction was 0.042, only slightly changed from the values found when these study subjects were included." (PMID 24278136, 2013). "Moreover, diseases correlated with NOS3 are Alzheimer’s, stroke, and obesity." (PMID 36532520, 2022). "Interestingly, we note a slightly significant enrichment for the endothelial nitric oxide synthase (NOS3) pathway (P = 0.026) in the obesity-T2D data, which may relate to impaired peripheral vascular integrity." (PMID 34553271, 2021). "Regarding the effects of variations in the NOS3 gene, studies indicate that decreased bioavailability of NO is also involved in the pathophysiology of metabolic diseases, such as T2DM and obesity." (PMID 32401924, 2020). "Active ingredients in WP, such as oxidized glutathione, may improve symptoms of HFD-induced obesity by acting on targets such as EGFR, NOS3, MMP2, PLG, PTGS2, and AR." (PMID 38162665, 2023). "Significant interactions were observed between NOS3 SNPs and HDL-C, triglycerides and obesity." (PMID 26437765, 2015). "We observed interactions between NOS3 SNP rs1800779 with HDL-C, triglycerides and obesity." (PMID 26437765, 2015).
Obesity (continued). "However, epidemiological studies reporting correlation between epigenetic signatures at the NOS3 gene locus in HUAEC and obesity as well as bone mineral content suggest that a hypoxia-induced epigenetic memory state might persist." (PMID 25699114, 2015).
Hyperglycemia (57 papers, 2012 to 2026). An increased concentration of glucose in the blood. "More specifically, hyperglycemia can reduce transcription at the Nos3 locus encoding for endothelial nitric oxide synthase, leading to increased expression of Jarid, a regulator of histone methyltransferase." (PMID 41153848, 2025). "Moreover, NOS3 G894T polymorphism is likely a predictor for persistent hyperglycemia for individuals who have a compromised glucose tolerance and atherogenic lipid profile in Asian populations." (PMID 29907847, 2018). "In linear regression analysis adjusted for age, gender, status for hyperglycemia, and smoking, only T allele of NOS3 was associated with increasing global DNA methylation with a beta coefficient of 0.943 (95% confidence interval: 0.286 to 1.560) assuming a log-additive genetic model." (PMID 27990443, 2016). "In HMVEC, we showed that the hyperglycemia induced an upregulation of NOS3 and NOS2 gene expression levels similar to previous study." (PMID 24093550, 2013). "Conversely, pharmacological activation of PKM2 using TEPP-46, a PKM2 selective activator that promotes PKM2 tetramerization while blocking its PKM2 nuclear translocation, ameliorated hyperglycemia-induced mitochondrial dysfunction and kidney injury in diabetic Nos3‐/‐ and DBA/2J mice." (PMID 35637461, 2022). "Moreover, both the genetic deletion of NOS3 and hyperglycemia (a state of impaired NOS3) abolished the benefits of IC." (PMID 36290774, 2022). "The increased formation of ROS in vascular cells in hyperglycemia also occurs through the activation of vascular NADPH oxidase (NOX) and the increased expression and uncoupling of endothelial nitric oxide synthase (NOS3), stimulated by upstream activation of PKC." (PMID 35216280, 2022).
coronary artery disease (51 papers, 2007 to 2025). "Polymorphisms such as T-786C and G894T in the eNOS (NOS3) gene are associated with impaired NO production and an increased risk of cardiovascular conditions, including hypertension and coronary artery disease." (PMID 39940974, 2025). "NOS3 (E298D and T-786C polymorphisms) was previously reported to be associated with the risk of incident coronary heart disease with the interaction of cigarette smoking." (PMID 41480028, 2025). "Our analysis shows a strong association of NOS3 with ischemic heart disease, underscoring its potential as both a therapeutic target and a biomarker for myocardial infarction and ischemic damage." (PMID 39594561, 2024). "Research has demonstrated that the Glu298Asp polymorphism (rs1799983) found in the endothelial nitric oxide synthase (NOS3) gene is linked to reduced levels of circulating nitric oxide and an elevated risk of coronary heart disease." (PMID 38952541, 2024). "A previous study in mice demonstrated that NOS3 deficiency increased atherosclerotic plaque formation and induced coronary artery disease and several cardiovascular complications, including spontaneous aortic aneurysm and dissection." (PMID 37239987, 2023). "In contrast, the same authors have shown that a common variant located in the NOS3 promoter and known to enhance eNOS production was strongly associated with a decreased risk of hypertension and coronary artery disease." (PMID 36941667, 2023). "The variant rs1799983 codes a missense Glu298Asp change in exon 7 of the Nitric Oxide Synthase 3 (NOS3) gene which is linked to coronary artery spasm, ischemic heart disease, ischemic stroke and resistant hypertension." (PMID 29334895, 2018). "The purpose of this updated meta-analysis was to investigate the effect of nitric oxide synthase-3 (NOS3) G894T polymorphisms, air pollution and their interaction on ischemic heart disease (IHD) risk across populations worldwide." (PMID 30071659, 2018). "Associations of the a allele of the VNTR in intron 4 of NOS3 with coronary artery disease and renal disease have been reported." (PMID 29132319, 2017). "Our findings were similar to some previous studies which had shown the association of the single nucleotide polymorphism (SNP) in the NOS3 gene (rs1799983) with the risk of coronary artery disease and venous thromboembolism (VTE)." (PMID 23922896, 2013). "The interaction between smoking and NOS3 polymorphisms has been assessed in several studies with regard to coronary artery disease, peripheral arterial disease, and cerebrovascular incidents." (PMID 22164159, 2011). "Since reduced NO synthesis in endothelial cells has been implicated in the development of coronary atherosclerosis, we investigated the association of NOS3 gene polymorphisms and coronary artery disease (CAD) in an Iranian population." (PMID 20103956, 2010). "Due to the protective roles of NO against important events during atherogenesis, the NOS3 gene has been identified as also having other roles in deciding susceptibility to coronary heart disease." (PMID 20103956, 2010). "In addition, there was also a study in mice that showed that NOS3 deficiency resulted in increased atherosclerotic plaque formation, which caused coronary artery disease along with other cardiovascular complications." (PMID 38790923, 2024). "The NOS3 gene encodes a protein involved in coronary artery disease, while the allele T of c.894G/T polymorphism might induce high blood pressure levels." (PMID 34440404, 2021). "Regarding the NOS3 gene, the SNPs rs2070744 and rs1799983 have been widely studied as possible risk factors for cardiovascular diseases, and rs1799983 was identified as a genetic biomarker of coronary artery disease in a meta-analysis of 132 case–control studies." (PMID 34290607, 2021). "Several association studies of endothelial nitric oxide synthase (NOS3) gene polymorphisms with respect to coronary artery disease (CAD) have been published in the past two decades." (PMID 25409023, 2014).
coronary artery disease (continued). "ACE and NOS3 are best known for their role in blood pressure regulation, but both are associated with 28 different diseases, including Alzheimer Disease, unstable angina, brain ischemia, coronary disease, systemic lupus erythematosus, preeclampsia, and autosomal dominant polycystic kidney disease." (PMID 19208189, 2009). "Evaluation of the clinical impact of these SNPs showed that polymorphism detected in nitric oxide synthase (NOS) 3 gene (NOS3), which encodes for endothelial NOS (eNOS), are correlated with ischemic heart disease." (PMID 30344267, 2018). "Together, these interactions underscore the complexity of redox signaling in the heart and highlight NOS3 as a critical player in oxidative damage during ischemic reperfusion, suggesting new pathways for redox-based therapeutic strategies in ischemic heart disease." (PMID 39594561, 2024). "This study aimed to analyze the single nucleotide polymorphism (SNP) of the NOS3 and DDAH2 genes and to identify their association with the risk of coronary artery disease (CAD)." (PMID 40144407, 2025). "In a study by Torres-Paz and colleagues, it was shown that monocytes from patients who had coronary artery disease (CAD) significantly increased the expression of both miR-21-5p and miR-221-5p and also decreased the expression of miR-155-5p and NOS3." (PMID 38790923, 2024).